APOB (apolipoprotein B)
Diseases named in the same sentence as APOB in open-access papers (continued):
Sharing a sentence is not in itself a finding about the gene and the disease.
aspergillosis (1 paper, 2020). Aspergillosis is an infection, growth, or allergic response caused by the Aspergillus fungus. "Interestingly, in our study protein levels for ApoB were significantly decreased in both hosts during aspergillosis; additionally, elevated levels for apolipoprotein E and N were detected in mice." (PMID 33043780, 2020).
Atherosclerotic lesion (1 paper, 2022). A lesion associated with atherosclerosis, a multifactorial and multipart progressive disease manifested by the focal development within the arterial wall of lesions, that ranges from the development of a fatty streak, plaque progression, and plaque disruption. "Immune intervention with Ox-ApoB-PF inhibits the occurrence and development of atherosclerotic lesions by protecting the vascular endothelial barrier function." (PMID 35391927, 2022).
Bell's palsy (1 paper, 2023). Partial or complete paralysis of the facial muscles of one side of a person's face. "However, after removing one outlier (rs143020224) which was detected by “leave-one-SNP-out” analysis, the relationship between apolipoprotein B and Bell’s palsy disappearred in the IVW (OR = 0.844, 95%CI = 0.706–1.010, p = 0.063)." (PMID 37533435, 2023). "The present study also showed that increased level of apolipoprotein B was almost associated with a reduced risk of Bell’s palsy, although this correlation was not statistically significant after excluding one outlier." (PMID 37533435, 2023).
benign breast tumor (1 paper, 2025). "Comparisons of the baseline characteristics in the groups with low or high levels of apoB in benign breast tumor patients, n (%) or median(IQR)." (PMID 40678973, 2025).
biliary tract cancer (1 paper, 2024). "In addition, both low and high levels of apolipoprotein B were associated with an increased risk of biliary tract cancer." (PMID 38434974, 2024).
bladder tumour (1 paper, 2022). "Mutational signatures show the anti-viral apolipoprotein B mRNA editing enzyme catalytic polypeptide (APOBEC) enzymes are responsible for the preponderance of mutations in bladder tumour genomes, but no causative viral agent has been identified." (PMID 35194151, 2022).
cataract (1 paper, 2019). Partial or complete opacity of the crystalline lens of one or both eyes that decreases visual acuity and eventually results in blindness.
colorectal polyps (1 paper, 2024). "ROC curve analyses revealed that TC, ApoB, and ApoB/ApoA1 ratio were associated with colorectal polyps." (PMID 39252808, 2024). "The TC, ApoB and ApoB/ApoA1 ratios were also linked to colorectal polyps, according to ROC curve analyses." (PMID 39252808, 2024). "The TC, TG, and ApoB/ApoA1 ratios were also linked to colorectal polyps, according to ROC curve analyses." (PMID 39252808, 2024). "According to multiple regression analysis, TC, TG, LDL-C, and ApoB may increase the incidence of colorectal polyps (p<0.05)." (PMID 39252808, 2024).
congestive heart failure (1 paper, 2020). Failure of the heart to pump a sufficient amount of blood to meet the needs of the body tissues, resulting in tissue congestion and edema. "Clinical trials have reported that BBR treatment reduced the levels of the cardiovascular risk indicators, such as LDL, and apolipoprotein B/apolipoprotein A1 (ApoB/ApoA1) ratios, and improved the quality of life in congestive heart failure patients in combination with conventional therapy." (PMID 32855766, 2020).
diabetic eye disease (1 paper, 2024). A group of disorders affecting the eye in patients with diabetes mellitus. "In the higher Lp(a) group, there were significantly elevated levels of diabetic eye disease, apoB, hs-CRP, TC, LDL-C, sdLDL-C, and HCY, compared to the lower Lp(a) group (p < 0.05)." (PMID 39296136, 2024). "Compared to the non-CHD group, the CHD group showed higher levels of family history of CHD, diabetic eye disease, statin drug therapy, serum sdLDL-C, LDL-C, apoB, TC and Lp(a) [41.70 (47.37) nmol/L vs. 37.97 (32.94) nmol/L, p < 0.001]." (PMID 39296136, 2024).
emphysema (1 paper, 2025). "Conversely, higher SFA intake was linked to elevated LDL-cholesterol and apolipoprotein B, which are implicated in impaired pulmonary function and increased emphysema burden." (PMID 40808839, 2025).
endometrioid carcinoma (1 paper, 2024). "Among the six lipid-lowering drug targets, we observed a significant association between lower predicted APOB levels and higher CETP levels with an increased risk of endometrioid carcinoma." (PMID 39193372, 2024). "In drug target Mendelian randomization, genetic modeling of apolipoprotein B (APOB) (OR [95%CI]=0.31, [0.16-0.60]; p=4.73e-04) and cholesteryl ester transfer protein (CETP) (OR [95%CI]=1.83, [1.38-2.43]; p=2.91e-05) genetic mimicry was associated with non-endometrioid carcinoma." (PMID 39193372, 2024).
esophageal adenocarcinoma (1 paper, 2021). A malignant tumor with glandular differentiation arising predominantly from Barrett mucosa in the lower third of the esophagus. "In contrast, esophageal adenocarcinomas show a steady decrease in SBS17 activity, whereas thyroid adenocarcinomas often display a continuing increase in SBS2/13 (apolipoprotein B mRNA editing enzyme, catalytic polypeptide-like or APOBEC)." (PMID 33831375, 2021).
frontotemporal dementia (1 paper, 2026). Frontotemporal dementia (FTD) comprises a group of neurodegenerative disorders, characterized by progressive changes in behavior, executive dysfunction and language impairment, as a result of degeneration of the medial prefrontal and frontoinsular cortices. "A recent study provided evidence that LDL and total cholesterol are implicated in ALS, and an increased ApoB level is related to ALS and frontotemporal dementia (FTD)." (PMID 41601590, 2026).
gallbladder polyps (1 paper, 2021). "However, B scan showed the gallbladder polyps and thyroid nodules, and blood test detected high total cholesterol, high low-density lipoprotein cholesterol, high apolipoprotein B, and high uric acid in the proband of family B." (PMID 33520300, 2021).
geographic atrophy (1 paper, 2024). "In a large genome-wide association study (GWAS), the ApoB level was associated with a lower risk of intermediate and geographic atrophy (GA) AMD, but not with the presence of CNV." (PMID 38792644, 2024).
glomerulonephritis (1 paper, 2021). A renal disorder characterized by damage in the glomeruli. "Immunocytochemical staining of renal biopsy specimens featuring various types of glomerulonephritis showed deposition of ApoE and ApoB in mesangium, sclerosed areas of glomeruli, and glomerular cells." (PMID 33633132, 2021).
HCMV infection (1 paper, 2017).
head and neck squamous cell carcinoma (1 paper, 2019). A squamous cell carcinoma that arises from any of the following anatomic sites: lip and oral cavity, nasal cavity, paranasal sinuses, pharynx, larynx, and salivary glands. "Mutational processes are of particular importance in head and neck squamous cell carcinoma (HNSCC) because of the high proportion of mutations that are attributed to APOBEC (apolipoprotein B mRNA editing catalytic polypeptide-like) enzymes in HNSCC tumors." (PMID 30647454, 2019).
Hernia (1 paper, 2018). "Apolipoproteins were analyzed with an immunoassay for multiplexed detection of APOA1, APOA2, APOB, APOC2, APOC3, and APOE, and all six proteins were found to be significantly elevated in urine samples of BC patients when compared to controls (hernia patient volunteers)." (PMID 30544619, 2018).
Hirsutism (1 paper, 2025). Abnormally increased hair growth referring to a male pattern of body hair (androgenic hair). "After adjusting for age and BMI, a significant linear relationship was observed between MAP and WC, WHR, hirsutism score, FBG, LDL, TG, TC, ApoB, and ApoB/ApoA1 ratio." (PMID 41040863, 2025).
HOMA-IR (1 paper, 2020). The HOMA-IR measurement employs the homeostatic model assessment (HOMA) to quantify insulin resistance. "Overall, there were significant differences (p < 0.05) between the LGI and control groups with respect to weight, glycated hemoglobin, insulin, Homa-IR, triglycerides, hs-CRP and ApoB." (PMID 32867226, 2020).
infectious meningitis (1 paper, 2022). Inflammation of the meninges of the brain and/or spinal cord caused by an infectious agent (viral, bacterial, or fungal). "A significantly higher expression of APOAI, APOB, and APOE in patients with TBM than those with other infectious meningitis indicated that the occurrence and progression of TBM are related to abnormal lipid metabolism." (PMID 36003300, 2022).
injury (1 paper, 2021). Damage inflicted on the body as the direct or indirect result of an external force, with or without disruption of structural continuity. "The ApoB/ApoA-Ι ratio can reflect the balance between the risk factors for and protective factors against kidney injury." (PMID 34627286, 2021). "Compared with ApoA-Ι or ApoB alone, it is considered a better predictor of the occurrence and progression of kidney injury." (PMID 34627286, 2021).
intrahepatic cholangiocarcinoma (1 paper, 2023). A carcinoma that arises from the intrahepatic bile duct epithelium in any site of the intrahepatic biliary tree. "APOB was also highlighted as a useful tool to predict resistance to treatment, where serum lipid levels of APOB as well as APOA1 were found to be useful in predicting the response of patients with advanced intrahepatic cholangiocarcinoma to PD-1 inhibitor treatment." (PMID 38067270, 2023).
keloid (1 paper, 2022). An irregularly shaped, elevated mark on the skin caused by deposits of excessive amounts of collagen during wound healing. "Mean Lp(a) (57.8 vs. 44.2 mg/dL; P = 0.01, OxPL-apoB 17.4 vs. 15.7 nmol/L; P = 0.009) and IgG and IgM apoB-immune complexes and IgG and IgM MDA-mimotope levels were significantly higher in keloid cases." (PMID 36320028, 2022). "This study demonstrates that darkly pigmented African subjects with keloid formation had significantly higher levels of Lp(a), OxPL-apoB, circulating IgG and IgM apoB-immune complexes and MDA-mimotope levels compared to the non-keloid control group." (PMID 36320028, 2022). "The immunohistochemistry data showed only faint apoB staining and could not identify the presence of apolipoprotein(a) in keloid tissue, suggesting that the Lp(a) holoparticle was not accumulating to any significant extent in the keloid tissue." (PMID 36320028, 2022).
kidney transplant (1 paper, 2015). A surgical procedure in which one or both kidneys from a donor are implanted into a recipient. "We examined associations of nitrated lipoproteins with serum levels of apoA-I and apoB in kidney transplant recipients." (PMID 26648662, 2015).
leukemia (1 paper, 2017). A malignant (clonal) hematologic disorder, involving hematopoietic stem cells and characterized by the presence of primitive or atypical myeloid or lymphoid cells in the bone marrow and the blood. "In addition, we confirmed 41 SNVs that had a strong enrichment for C to T transitions and C to G transversions within an apolipoprotein B mRNA editing catalytic polypeptide-like (APOBEC) motif, in agreement with previous studies of this subtype of leukemia." (PMID 29178827, 2017).
leukopenia (1 paper, 2023). "In addition, our results showed that patients with leukopenia had higher blood CH and ApoB levels than normal patients before and after treatment." (PMID 37441519, 2023). "After the administration of thiopurines, CH (p = 0.02), HDL (p = 0.01), ApoA1 (p = 0.01), and ApoB (p = 0.03) had higher levels in the leukopenia group compared to the non-leukopenia group." (PMID 37441519, 2023).
leukoplakia (1 paper, 2024). A white patch or plaque on a mucous membrane that cannot be characterized clinically or pathologically as any other disease. "In our forward Mendelian randomization analysis, ApoB was found to contribute to the development of oral leukoplakia in 35 biomarkers of blood and urine even after Bonferroni correction (IVW: P<0.0007)." (PMID 39239270, 2024). "Changes in non-albumin proteinuria may be suggestive of a marker of leukoplakia malignancy, while how changes in apolipoprotein B contribute to oral leukoplakia still requires further study." (PMID 39239270, 2024).
lung fibrosis (1 paper, 2023). "Previous studies on ApoB and lung fibrosis are limited, with most focusing on fibrosis in other organs such as the heart, liver, and kidney." (PMID 38260151, 2023).
male infertility (1 paper, 2024). The inability of the male to effect fertilization of an ovum after a specified period of unprotected intercourse. "In sum, our study identified a potential association between the APOB rs13306194 variant and male infertility in obese patients." (PMID 38730451, 2024). "Our findings reveal a novel association between differential APOB expression and male infertility." (PMID 38730451, 2024). "We identified 187 obesity-related genes and 195 male infertility-related genes from the OMIM database, with the Apolipoproteins B (APOB) gene shared between the two datasets." (PMID 38730451, 2024).
metastatic melanoma (1 paper, 2017). A melanoma that has spread from its primary site to another anatomic site. "Genes encoding high-mobility group protein A1 (HMGA1), Kv Channel Interacting Protein 3 (KCNIP3) and Apolipoprotein B (APOB) shared promoter hypomethylation in all metastatic melanoma cell lines." (PMID 28030832, 2017).
mood disorder (1 paper, 2025). A cognitive disorder a disturbance in which the person's mood is hypothesized to be the main underlying feature. "In addition, apolipoproteins, particularly apolipoprotein A1 (ApoA1) and apolipoprotein B (ApoB), play a role in lipid transport and inflammation implicated in mood disorders." (PMID 41220462, 2025).
motor neuron degeneration (1 paper, 2022). "Targeted depletion of apolipoprotein B-100 in CSF via immunodepletion or CSF filtration attenuates its neurotoxic capacity, thereby preventing induction of disability and motor neuron degeneration." (PMID 36043141, 2022). "Myelin oligodendrocyte glycoprotein (MOG), haptoglobin, apolipoprotein C-III (ApoC-III), and apolipoprotein E (ApoE), all failed to recapitulate the motor disability and motor neuron degeneration observed with sALS CSF and ApoB." (PMID 36043141, 2022).
myopia (1 paper, 2019).
nasopharyngeal carcinoma (1 paper, 2020). A carcinoma arising from the nasopharyngeal epithelium. "The aim of this study was to investigate the correlation between ApoB/ApoA1 ratio and the severity of radiation‐induced brain necrosis (RN) in patients who underwent radiotherapy after nasopharyngeal carcinoma (NPC)." (PMID 32017458, 2020).
neck cancers (1 paper, 2020). "Recent evidence has implicated APOBEC3B (Apolipoprotein B mRNA editing enzyme catalytic subunit 3B) as a source of mutations in breast, bladder, cervical, lung, head, and neck cancers." (PMID 32934779, 2020).
nonalcoholic steatohepatitis (1 paper, 2023). "Treatment with acetyl-CoA carboxylase inhibitors (ACCi) in nonalcoholic steatohepatitis (NASH) may increase plasma triglycerides (TGs), with variable changes in apoB concentrations." (PMID 36737040, 2023).
peanut allergy (1 paper, 2014). "We undertook this study to investigate whether there is a correlation between PAF-AH activity and apolipoprotein B concentrations in patients with peanut allergy." (PMID 24808915, 2014). "In this study, our aim was to investigate whether PAF-AH activity correlates with apoB, the main surface protein on LDL particles, in patients with peanut allergy." (PMID 24808915, 2014).
periodontal disease (1 paper, 2025). "In particular, permeability changes in apoB were markedly enhanced by hyperglycaemia rather than by inflammation associated with periodontal disease." (PMID 41465350, 2025). "In addition, longitudinal studies are required to clarify how changes in GCF oxLDL/apoB correspond to periodontal disease progression, systemic metabolic conditions, and treatment outcomes." (PMID 41465350, 2025).
plague (1 paper, 2022). Plague is a severe bacterial infection caused by the gram-negative bacterium Yersinia pestis. "A cohort study shows that apoB/apoA1 ratio is an independent predictor for patients with atherosclerotic cardiovascular disease (ASCVD) who are attacked by plague rupture, erosion or thrombus." (PMID 36445669, 2022).
plasma cell neoplasm (1 paper, 2023). A clonal proliferation of immunoglobulin-secreting plasma cells. "Low serum total cholesterol, LDL, HDL, ApoA, and ApoB levels were all associated with increasing the risk of plasma cell neoplasm." (PMID 37908181, 2023). "We also found that TC, LDL, and ApoB level, which were considered as bad particles unexpectedly presented the same effects as HDL and ApoA on the risk of plasma cell neoplasms." (PMID 37908181, 2023). "Overall, we found that lower levels of TC, HDL, LDL, ApoA, and ApoB were related to a higher risk of plasma cell neoplasms but triglyceride levels did not have the association." (PMID 37908181, 2023).
pulmonary diseases (1 paper, 2018). "ApoB has a proven role in atherosclerotic diseases of the cardiovascular system, but its role in the pathogenesis of pulmonary disease is not determined yet." (PMID 30627178, 2018).
retinal diseases (1 paper, 2020). "A higher level of ApoB and a lower level of ApoA1 may contribute to the risk of RE-related retinal diseases." (PMID 33614678, 2020).
selenium deficiency (1 paper, 2005). A nutritional deficiency disease resulting from inadequate selenium levels in the body, which can lead to impaired function of selenoproteins essential for antioxidant defense and thyroid hormone metabolism. "As T3 is involved in LDL-R expression, so reduced T3 levels during selenium deficiency is responsible for increase in apoB levels." (PMID 16271152, 2005). "In selenium deficiency and on high cholesterol diet (HCD) feeding apoB levels increased and LDL-R expression decreased significantly after 2 months." (PMID 16271152, 2005). "So no change was there in apoB expression on high cholesterol diet feeding as well as in selenium deficiency and on 1 ppm selenium supplementation." (PMID 16271152, 2005). "Selenium deficiency leads to decreased expression of 5'-DI, decreased T3 levels and decrease in LDL-cholesterol removal from blood through downregulation of LDL-R mRNA expression, ultimately decreased apoB catabolism through LDL receptors." (PMID 16271152, 2005).